ASAP3 (ArfGAP with SH3 domain, ankyrin repeat and PH domain 3)
Description:
Promotes cell proliferation.
Synonyms: DDEFL1; UPLC1; FLJ20199; CENTB6; ACAP4
Tractability: Small molecule: a structure with a bound ligand is known; it has a high-quality binding pocket. PROTAC: ubiquitination databases record sites on it.
Gene: Protein-coding gene on chromosome 1 (23,428,561 to 23,484,637, reverse strand). Ensembl gene ENSG00000088280.
Subcellular location: Cytoplasm
Subcellular location (Human Protein Atlas): Vesicles; Nucleoplasm
Gene Ontology:
Molecular function: GTPase activator activity; protein binding
Biological process: cell migration; positive regulation of GTPase activity; regulation of stress fiber assembly
Cellular component: focal adhesion; ruffle; plasma membrane; cytoplasm
Genetic constraint (gnomAD): Loss-of-function variants: 84 observed, 116.57 expected, observed/expected ratio (o/e) 0.72, 90% interval 0.6 to 0.86. The upper end of that interval is the gene's LOEUF score, 0.86, which puts it in group 3 of 6, group 1 being the genes least tolerant of losing a copy. Missense variants: 965 observed, 1,132.5 expected, observed/expected ratio (o/e) 0.85, 90% interval 0.81 to 0.9. Synonymous variants: 402 observed, 445.66 expected, observed/expected ratio (o/e) 0.9, 90% interval 0.83 to 0.98.
Homologues: Orthologues: chimpanzee ASAP3 (99% identical), macaque ASAP3 (97% identical), pig ASAP3 (89% identical), guinea pig ASAP3 (88% identical), dog ASAP3 (85% identical), rabbit ASAP3 (85% identical), mouse Asap3 (82% identical), rat Asap3 (81% identical). Paralogues in human: ASAP2 (47% identical), ASAP1 (45% identical), ACAP3 (21% identical), ACAP2 (20% identical), ACAP1 (18% identical), ARAP3 (17% identical), ARAP1 (17% identical), AGAP2 (17% identical), ARAP2 (16% identical), AGAP1 (16% identical), AGAP3 (16% identical), AGAP4 (12% identical), and 16 more.
Diseases named in the same sentence as ASAP3 in open-access papers:
ASAP3 is named in the same sentence as 35 diseases in open-access papers, as found by Europe PMC text mining. Sharing a sentence is not in itself a finding about the gene and the disease. The quoted sentences say what the papers report.
breast carcinoma (7 papers, 2017 to 2025). "It has been revealed that ASAP3 was unable to bind to invadopodia in breast cancer cells or podosomes in NIH3T3 mouse fibroblasts." (PMID 36382054, 2022). "In breast cancer cells transfected with plasmids overexpressing active or inactive ASAP3, cellular vinculin or paxillin in focal adhesion and the distribution of invadopodia were not affected." (PMID 36382054, 2022). "Consistent with our results, the oncogenic functions of ASAP3 have also been verified in lung cancer as well as breast cancer." (PMID 31186064, 2019).
hepatocellular carcinoma (5 papers, 2017 to 2025). A malignant tumor that arises from hepatocytes. "ASAP3 was initially found as a widely upregulated gene that leads to cell proliferation in hepatocellular carcinoma." (PMID 36382054, 2022). "DDEFL1 (cloned ASAP3) is unregulated in hepatocellular carcinoma (HCC) through microarray analysis." (PMID 33371893, 2020).
colorectal cancer (3 papers, 2022 to 2025). A primary or metastatic malignant neoplasm that affects the colon or rectum. "MiR‐143‐3p targeting integrin α 6 (ITGA6) and with SH3 domain, anchor protein repeat sequence and PH domain 3 (ASAP3), and promote the occurrence and development of colorectal cancer by regulating the expression of both proteins." (PMID 39823268, 2025). "ASAP3 is increased in lung and colorectal cancers with metastasis, which promotes the course of malignant disease and indicates poor patient survival." (PMID 36382054, 2022). "According to the Oncomine database, ASAP3 expression was higher in cervical cancer, colorectal cancer, gastric cancer, kidney cancer, melanoma, and lymphoma tumors in cancer histology." (PMID 36382054, 2022). "miRNA-143-3p reportedly inhibits the metastases of colorectal cancer by targeting ASAP3." (PMID 36829221, 2023).
glioma (2 papers, 2019 to 2022). A benign or malignant brain and spinal cord tumor that arises from glial cells (astrocytes, oligodendrocytes, ependymal cells). "Previous studies have shown that ASAP3 is associated with glioma biology." (PMID 36382054, 2022). "ASAP3 expression was related to the isocitrate dehydrogenase-1 mutation in low-grade glioma." (PMID 36382054, 2022). "However, the molecular processes underlying ASAP3 overexpression and the role of ASAP3 in glioma progression remain largely unknown." (PMID 36382054, 2022). "Glioma patients with high ASAP3 mRNA expression had a worse overall survival and progression-free survival." (PMID 36382054, 2022). "The expression of ASAP3 was an independent prognostic factor for the OS of glioma, and the expression of ASAP3 was positively correlated with that of NOTCH3 and Ki-67 expression rate." (PMID 36382054, 2022). "This study is intended to evaluate the potential biological function of ASAP3 in the progression of adult glioma." (PMID 36382054, 2022). "The TCGA database was used to derive ASAP3 expression levels in glioma from the TMA data in the library." (PMID 36382054, 2022). "Future studies on the molecular interaction of ASAP3 and its potential role in the development of glioma will be helpful for a better understanding of the development of this malignant tumor and the clinical tactics of therapy." (PMID 36382054, 2022). "Gene Expression Profiling Interactive Analysis (GEPIA) was used to validate the expression of ASAP3 as well as the correlation of NOTCH signaling pathway proteins in gliomas." (PMID 36382054, 2022). "The results revealed that the amount of ASAP3 mRNA in gliomas was much higher than in normal tissue (P < 0.01)." (PMID 36382054, 2022). "According to the median expression, the 676 glioma patients were split into the ASAP3 high expression group (n = 338) and the ASAP3 low expression group (n = 338)." (PMID 36382054, 2022). "We demonstrated for the first time that ASAP3 and NOTCH3 are substantially associated in human glioma samples." (PMID 36382054, 2022). "Remarkably, ASAP3 knockdown significantly inhibited the malignant biological behaviors of glioma cells such as cell proliferation, migration and invasion, while facilitating cell apoptosis." (PMID 31186064, 2019). "The Cell Counting Kit-8 assay, migration and invasion assays, and flow cytometry analysis were conducted to evaluate the function of A1CF, FAM224A, miR-590-3p, ZNF143 and ASAP3 in the malignant biological behaviors of glioma cells." (PMID 31186064, 2019). "CCK-8 assay, flow cytometry analysis and migration and invasion assays were used to measure the biological behaviors of glioma cells treated with ASAP3 overexpression or knockdown." (PMID 31186064, 2019). "Our study demonstrated that the high expression of ASAP3 in gliomas was closely related to age, high WHO grade, recurrence, resection, postoperative radio-chemotherapy, and Ki-67 expression ≥10%, suggesting that ASAP3 was strongly associated with cell proliferation and migration." (PMID 36382054, 2022). "Accordingly, ASAP3 may serve as a prognostic indicator and a potential treatment target in adult glioma." (PMID 36382054, 2022). "We used the GEPIA database to analyze the prognostic value of ASAP3 expression in glioma." (PMID 36382054, 2022). "Therefore, ASAP3 and NOTCH3 are interconnected with each other and associated with the development of adult glioma." (PMID 36382054, 2022). "Our findings showed that ASAP3 may play a significant role in the aggressiveness and progression of gliomas." (PMID 36382054, 2022). "According to the results, there may be a correlation between ASAP3 expression and the molecular subtypes of adult glioma." (PMID 36382054, 2022). "In adult glioma, we explore the effects of ASAP3 and NOTCH3 and their relationships on prognosis." (PMID 36382054, 2022). "ASAP3 may be combined with EGFR to arouse NOTCH3 expression to promote adult glioma proliferation and invasion." (PMID 36382054, 2022).
glioma (continued). "Although it has been reported that the expression of ASAP3 is elevated in glioma, its prognostic value and relationship with the expression of the cooperative protein NOTCH3 remain unclear." (PMID 36382054, 2022). "We constructed univariate and multivariate analyses of OS and PFS in adult glioma patients so that we could evaluate the clinical characteristics of these patients and the prognostic significance of the expression of the ASAP3 and NOTCH3 proteins." (PMID 36382054, 2022). "This evidence inferred that ASAP3 served as an oncogene in glioma cells." (PMID 31186064, 2019). "Furthermore, ZNF143 promoted the malignant biological behaviors of glioma cells by stimulating ASAP3 and MYB expression." (PMID 31186064, 2019). "The ASAP3 expression of glioma cells after ASAP3 overexpression or knockdown was examined." (PMID 31186064, 2019). "ASAP3 was dramatically upregulated in glioma tissues and cells compared with NBTs and NHA." (PMID 31186064, 2019). "Furthermore, overexpression of ZNF143 reversed the inhibitory effects of overexpressed miR-590-3p on glioma cell progression via upregulating ASAP3 and MYB expression." (PMID 31186064, 2019). "In our study, the expression levels of ASAP3 were remarkably elevated in glioma tissues and cells." (PMID 31186064, 2019). "However, due to the single experimental method in this study, the mechanism of ASAP3 in glioma through regulation of the NOTCH3 signaling pathway needs to be further verified at the cellular level and in animal models so as to further confirm the mechanism of ASAP3 in glioma." (PMID 36382054, 2022). "In addition, knockdown of ASAP3 dramatically hindered the biological behaviors of glioma cells." (PMID 31186064, 2019). "However, the biological function of ASAP3 in glioma is still undefined." (PMID 31186064, 2019). "We analyzed the correlation between ASAP3 expression levels and the OS and PFS of 676 glioma patients." (PMID 36382054, 2022). "Based on database comparison and literature assessment, the role of the relationship between ASAP3 and NOTCH3 in glioma has attracted the research group's interest among the 21 ASAP3 interacting proteins evaluated in the NOTCH signaling pathway." (PMID 36382054, 2022). "Immunohistochemistry was used to detect the protein expression of ASAP3, NOTCH3, and their relationship with clinicopathological features in all cohorts in order to study the potential function of ASAP3 and NOTCH3 in the progression of adult glioma." (PMID 36382054, 2022). "In univariate survival analysis, Age, tumor location, local recurrence, tumor resection, WHO grade, Ki-67 expression, ATRX expression, ASAP3 expression, and NOTCH3 expression were the significant prognostic factors for PFS in adult gliomas." (PMID 36382054, 2022). "Multivariate prognostic analysis showed that age, tumor site, WHO grade, recurrence, Ki-67 expression, IDH1 mutant, ATRX, ASAP3, and NOTCH3 expression were shown to be independent predictive determinants of overall survival in gliomas." (PMID 36382054, 2022). "We analyzed the relationship between the expression of ASAP3 and NOTCH3 and the clinicopathological parameters of 211 adult gliomas using TMA." (PMID 36382054, 2022). "However, ASAP3 may be involved in the process of glioma regulation." (PMID 36382054, 2022). "The following prognostic factors influence the OS in adult glioma: Age, tumor location, local recurrence, tumor resection, WHO grade, Ki-67 expression, ATRX expression, ASAP3 expression, and NOTCH3 expression." (PMID 36382054, 2022). "According to the results of our study, further analysis of ASAP3 and NOTCH3 co-expression in survival analysis in adult gliomas." (PMID 36382054, 2022). "Our results suggested that overexpression of miR-590-3p obviously reduced the expression of ASAP3 and MYB, thereby restraining the biological behaviors of glioma cells." (PMID 31186064, 2019).
glioma (continued). "To validate our assumption, we firstly detected the expression of ASAP3 and MYB in glioma cells treated with altered expression levels of miR-590-3p and ZNF143 expression." (PMID 31186064, 2019). "In our further studies, the ASAP3 and MYB expression of glioma cells treated with altering miR-590-3p and ZNF143 expression levels was detected." (PMID 31186064, 2019). "The function of ASAP3 in glioma has not been deeply comprehended in recent years, despite a number of studies on the abnormal expression of RNA and proteins in malignancies." (PMID 36382054, 2022). "Meanwhile, ASAP3 and NOTCH3 co-expression correlated with poorer OS and PFS in glioma patients." (PMID 36382054, 2022). "In adult glioma, the high expression of NOTCH3 is related to the overexpression of ASAP3." (PMID 36382054, 2022). "We speculated that ASAP3, as an upstream factor of the NOTCH3 signaling pathway, may promote glioma proliferation by regulating the expression of NOTCH3, thus affecting the development and prognosis of glioma." (PMID 36382054, 2022). "Therefore, ASAP3 and NOTCH3 as oncogene factors have the potential to be prognostic biomarkers and therapeutic targets in adult glioma." (PMID 36382054, 2022). "We intend to investigate the biological function of ASAP3 and its closely related protein NOTCH3, as well as provide new hints for molecularly targeted glioma therapy, by elucidating the expression and clinical significance of ASAP3 in adult glioma." (PMID 36382054, 2022). "Therefore, ASAP3 and MYB are involved in mediating the regulatory effects of miR-590-3p on glioma cell progression, after being activated by ZNF143." (PMID 31186064, 2019). "Overall, these findings indicated that miR-590-3p could impede ASAP3 and MYB expression by downregulating ZNF143 in glioma cells." (PMID 31186064, 2019). "Inhibiting ASAP3 and NOTCH3 co-expression may improve the prognosis of glioma patients." (PMID 36382054, 2022). "The high expression of ASAP3 and NOTCH3 could predict the short OS in adult glioma." (PMID 36382054, 2022). "However, there is scarcely any research that investigates whether or not there is a correlation between the expression of ASAP3 and the prognosis of glioma patients." (PMID 36382054, 2022). "Therefore, ASAP3 and NOTCH3 may be the potential biomarkers of poor prognosis in adult glioma." (PMID 36382054, 2022). "MiR-590-3p could bind to the ZNF143 3′ UTR and repress the expression of ASAP3 and MYB by negative modulation of ZNF143, thereby hindering the malignant progression of glioma cells." (PMID 31186064, 2019).
diffuse large B-cell lymphoma (1 paper, 2022). "Meanwhile, the results showed that the expression of ASAP3 mRNA was also significantly higher in other cancer types: Lymphoid Neoplasm Diffuse Large B-Cell Lymphoma (DLBC), Brain LGG, and Thymoma (THYM)." (PMID 36382054, 2022).
gastric ulcer (1 paper, 2017). An ulcerated lesion in the mucosal surface of the stomach. "The subjects expressing high level of ASAP3 (top 25%) were found with significantly more gastric ulcer than other subjects." (PMID 29263912, 2017).
Glioblastoma multiforme (1 paper, 2022). "The results of the TIMER database analysis showed that ASAP3 expression was significantly higher in GBM (Glioblastoma multiforme), kidney chromophobe (KICH), and liver hepatocellular carcinoma (LIHC) compared with adjacent normal tissues." (PMID 36382054, 2022). "Immunohistochemistry revealed that ASAP3 and NOTCH3 were overexpressed in glioblastomas (GBMs)." (PMID 36382054, 2022).
osteosarcoma (1 paper, 2022). A usually aggressive malignant bone-forming mesenchymal neoplasm, predominantly affecting adolescents and young adults. "We individually depleted ASAP1, ASAP2, or ASAP3 in U2OS human osteosarcoma cells using SMARTpool siRNAs, replated the cells on fibronectin in serum-free media, stained the cells with fluorescent phalloidin, and examined them using laser scanning confocal microscopy." (PMID 35143843, 2022).
ovarian carcinoma (1 paper, 2023). A malignant neoplasm originating from the surface ovarian epithelium. "Interestingly, none of the four top genes WBP1L, ASAP3, CNNM2, and NCAPH2 was correlated with ovarian cancer pathogenesis previously." (PMID 36856946, 2023).
Peptic ulcer (1 paper, 2017). The term peptic ulcer refers to acid peptic injury of the digestive tract, resulting in mucosal break reaching the submucosa. "Of note, the expression of ASAP3 was positively correlated with gastric acid secretion in 90 human cases, and high expression of ASAP3 was associated with reflux disease and peptic ulcer." (PMID 29263912, 2017).
cancer (9 papers, 2015 to 2025). A tumor composed of atypical neoplastic, often pleomorphic cells that invade other tissues. "ASAP3 (ArfGAP With SH3 domain, ankyrin repeat and PH domain 3) promotes cell differentiation and migration and has been previously linked to cancer cell invasion." (PMID 36856946, 2023). "The high expression of ASAP3 in GBM (80.82%) suggested that ASAP3 is activated more frequently in the most aggressive and malignant tumors." (PMID 36382054, 2022). "It is possible that ASAP3 is involved in the regulation of cell migration and, as a result, the invasion of cancer cells." (PMID 36382054, 2022). "ASAP3 is involved in a variety of biological activities, including cancer progression in humans." (PMID 36382054, 2022). "A total of 20 target mRNAs of three miRNAs were predicted, among which seven target mRNAs—ASAP3, BCL2L2, LMF1, PPM1L, PTPN21, SLC18A2, and NR3C2—had prognostic value; PRKACB, PDCD4, RPS6KA5, and BCL2L2 were enriched in the miRNA cancer pathway." (PMID 36829221, 2023). "In some types of cancer cells, ACTG1 instability can lead to decreased ASAP3 expression, which inhibits cell migration and invasion." (PMID 38077434, 2023).
tumor (6 papers, 2017 to 2025). "ASAP3 expression was associated with age, recurrence, tumor resection, postoperative chemoradiotherapy, World Health Organization (WHO) grade, and Ki-67 expression." (PMID 36382054, 2022). "We determined the expression difference of ASAP3 between tumor tissues and normal tissues through multiple databases." (PMID 36382054, 2022). "Whereas, overexpression of ZNF143 reversed the miR-590-3p-mediated tumor-suppressive effects through elevating ASAP3 and MYB expression." (PMID 31186064, 2019). "Multivariate analysis (Cox’s proportional hazards regression model) showed that the possible independent prognostic factors for OS were as follows: Age, tumor location, local recurrence, tumor resection, WHO grade, Ki-67 expression, and ATRX expression, ASAP3 expression, and NOTCH3 expression." (PMID 36382054, 2022).
ASAP3 also shares sentences with these, for which no sentence is quoted: lung carcinoma (3 papers); bladder urothelial carcinoma (1); cervical cancer (1); colon adenocarcinoma (1); colon cancer (1); esophageal carcinoma (1); gastric cancer (1); head and neck cancer (1); invasive breast carcinoma (1); kidney cancer (1); liver cancer (1); lung adenocarcinoma (1); lung squamous cell carcinoma (1); lymph node metastasis (1); lymphoid neoplasm (1); melanoma (1); non-small cell lung carcinoma (1); Pheochromocytoma and Paraganglioma (1); rectum adenocarcinoma (1); stomach adenocarcinoma (1); thymoma (1); thyroid carcinoma (1); uterine corpus endometrial carcinoma (1).